CXCL10 (C-X-C motif chemokine ligand 10)
Diseases named in the same sentence as CXCL10 in open-access papers (continued):
Sharing a sentence is not in itself a finding about the gene and the disease.
unstable angina (3 papers, 2014 to 2018). "Patients with acute myocardial infarction (AMI) showed significantly higher serum levels of CXCL10 than control subjects and patients with stable angina pectoris." (PMID 27795961, 2016). "Patients suffering from unstable angina showed an increased CXCL10 expression in PBMCs as early as 6 hours after onset of complaints compared to controls or patients suffering from stable angina." (PMID 24868552, 2014). "However, the levels of CXCL9, CXCL10, and CXCR3 remained low in patients with unstable angina, comparable to the control group and significantly lower than in patients with stable angina." (PMID 30210493, 2018). "It would be interesting to test blood concentration of CXCL10 within the first 3 hours after angina onset during AMI when systemic activation is not yet started." (PMID 27795961, 2016).
vivax malaria (3 papers, 2014 to 2019). "The SNPs were assessed regarding association with systemic levels of TNF, IL-6, CXCL10, and CRP, which have been associated with vivax malaria manifestations." (PMID 25038626, 2014). "Asymptomatic vivax malaria patients presented a similar number of variables with significant concentrations increases (mainly IFN-γ, IL-10 and direct bilirubin) and decreases (such as CXCL10, IL-1β, IL-4 and indirect bilirubin)." (PMID 31233500, 2019).
acute disseminated encephalomyelitis (2 papers, 2020 to 2021). Acute disseminated encephalomyelitis (ADEM) is a demyelinating disorder of the central nervous system. "Experiment has shown that CoVs play a destructive role in acute disseminated encephalomyelitis (ADEM) correlated with increased inflammatory mediators such as IL-6, IFN-γ, TNF-α, CXCL9, and CXCL10." (PMID 33708124, 2020).
amyotrophic lateral sclerosis (2 papers, 2025). Amyotrophic lateral sclerosis (ALS) is a neurodegenerative disease characterized by progressive muscular paralysis reflecting degeneration of motor neurons in the primary motor cortex, corticospinal tracts, brainstem and spinal cord. "For example, Tregs expressing integrin protein CD11a, in the case of CK0803 for trial NCT05695521, have been used to target the CXCR3/CXCL10 axis with the aim of engaging the inflamed microglia in patients with amyotrophic lateral sclerosis (ALS)." (PMID 41246323, 2025).
ANCA-associated vasculitis (2 papers, 2024). "Yokoseki also reported increased levels of IL-6, C-X-C motif ligand (CXCL)-8, and CXCL-10/IFN-γ inducible protein (IP)-10 in cerebrospinal fluid of HP with ANCA-associated vasculitis or IgG4-RD." (PMID 38988571, 2024).
Ataxia (2 papers, 2011 to 2021). Ataxia refers to impaired coordination of voluntary muscle movement. "Raised serum β2M and HTLV-1 PVL > 1% in blood and higher in CSF, as well as elevated concentrations of neopterin and CXCL10 in CSF support the notion of a putative association between cerebellar ataxia and HTLV-1." (PMID 33751488, 2021). "During infection with P. berghei, WT mice exhibited characteristic symptoms as expected of murine CM including ruffled furs, weakness and ataxia compared with the CXCL-10-/- mice." (PMID 21439091, 2011).
Atherosclerotic lesion (2 papers, 2015 to 2022). A lesion associated with atherosclerosis, a multifactorial and multipart progressive disease manifested by the focal development within the arterial wall of lesions, that ranges from the development of a fatty streak, plaque progression, and plaque disruption. "CXCR3 receptor is activated by IFN-γ-inducible chemokines such as CXCL9, CXCL10 (IP-10), and CXCL11 (I-TAC), which are highly expressed in atherosclerotic lesions and play an important role in Th1-cell homing." (PMID 25873769, 2015).
autism (2 papers, 2021 to 2024). Persistent deficits in social interaction and communication and interaction as well as a markedly restricted repertoire of activity and interest as well as repetitive patterns of behavior. "The association between cord blood CXCL10 and autism likelihood was aOR 1.28 (95% CI 1.10." (PMID 39247132, 2024). "For example, CXCL10, one of the genes that we identified as being up-regulated in mothers whose infants were at high likelihood of autism, was higher in maternal blood of autistic males compared to male controls and mothers of autistic females with autism compared to female controls." (PMID 39247132, 2024). "Six genes were significantly differentially expressed between autism likelihood (social communication) groups: CYSLTR2, NOX1, C1QA, CXCL10, C8A, IL23R (all up-regulated, p < 0.05)." (PMID 39247132, 2024).
babesiosis (2 papers, 2023 to 2025). Babesiosis refers to a condition caused by microscopic parasites that infect the red blood cells. "Moreover, CXCL10 is associated with warm autoimmune hemolytic anemia in humans, and this type of hemolysis has been recognized in humans after babesiosis." (PMID 36839438, 2023).
bipolar disorder (2 papers, 2018 to 2019). A disorder of the brain that causes unusual shifts in mood, energy, activity levels and the ability to carry out day-to-day tasks. "Soon after, we evaluated the serum levels of a set of chemokines (CCL2, CCL3, CCL11, CCL24, CXCL8, CXCL9, CXCL10) in 30 euthymic patients with bipolar disorder and 30 matched controls." (PMID 29962972, 2018). "Patients with bipolar disorder showed increased levels of IP-10/CXCL10, lower levels of eotaxin-2/CCL24 and similar levels of the other chemokines compared to controls." (PMID 29962972, 2018). "Taking into account that IP-10/CXCL10 is associated with a Th1 response, and eotaxin-2/CCL24 (as eotaxin-1/CCL11) is related to a Th2 response, this result suggested an imbalance of Th1/Th2 cytokines toward a Th1 profile in bipolar disorder." (PMID 29962972, 2018). "Inflammation can also play an important role in the etiology of bipolar disorder, which has been suggested by several studies, in which patients with bipolar disorder showed increased levels of CCL11 and CXCL10 in the plasma." (PMID 31075818, 2019).
bladder tumors (2 papers, 2011 to 2015). "Both MB49 and MBT-2 cells express the chemokine CXCL10 (IP10) as do human bladder tumors and this chemokine has proinflammatory and angiostatic effects in the tumor microenvironment." (PMID 22013484, 2011). "We observed that bladder tumors uniformly expressed only low levels of CTL attracting chemokines: CCL5, CXCL9, and CXCL10 (respective ligands for CTL-expressed CCR5 and CXCR3)." (PMID 25806105, 2015).
bone metastasis (2 papers, 2021 to 2024). Transfer of a neoplasm from its primary site to bones. "Among these genes, NCAM1 expressed higher in bone metastasis group, while CXCL10 and C3 expressed lower in bone metastasis group." (PMID 33859877, 2021).
brain infarction (2 papers, 2018 to 2022). Tissue necrosis in any area of the brain, including the cerebral hemispheres, the cerebellum, and the brain stem. "Here, we demonstrated that EGB markedly reduced pro-inflammatory cytokines/chemokines levels, including those of IL-6, IL-α and CXCL10, in tissues surrounding the cerebral infarction." (PMID 29867513, 2018).
bronchiolitis (2 papers, 2024). Inflammation of the bronchioles characterized by swelling of the bronchioles and mucus accumulation. "Accordingly, previous studies have reported an inverse association between CXCL10 levels in the nasopharynx and the severity of bronchiolitis, particularly regarding hospitalization rates in RSV-infected children." (PMID 39403383, 2024).
brucellosis (2 papers, 2024 to 2025). Brucellosis is a bacterial infection that spreads from animals to people via unpasteurized dairy products or by exposure to contaminated animal products or infected animals. "Additionally, we also detected high expression of typical inflammatory cytokines (e.g., S100A8/9/12, IL1B, IL6, CXCL8, CCL2, CXCL10) in brucellosis patients during the acute phase." (PMID 39135683, 2024).
bullous pemphigoid (2 papers, 2019 to 2023). Bullous pemphigoid (BP) is the most common form of autoimmune bullous dermatosis. "In patients with bullous pemphigoid, monocyte-derived macrophages, but not lymphocytes, respond to CXCL10 (upregulated by IL-17) by increasing MMP-9 release, potentially creating an inflammatory loop associated with disease outcome." (PMID 36911370, 2023). "Recently, MMP9 level was found to be induced by CXCL10 from monocytes and neutrophils but not lymphocytes in bullous pemphigoid patients, suggesting that the increased MMP9 in PBMCs stimulated with purified IgG from Jo1-positive sera, was perhaps due to monocytes." (PMID 31440381, 2019).
Burkitt lymphoma (2 papers, 2017 to 2021). A rare form of malignant mature B-cell non-Hodgkin lymphoma. "In xenograft models, CXCL9 and CXCL10 has been shown to inhibit Burkitt’s lymphoma tumours established in nude mice." (PMID 28588211, 2017). "Indeed, IL12 increased the production of cytolytic mediators as granzyme and perforin by NK cells and blocked the pro-angiogenic effect of FGF2 by IP-10 (CXCL10), causing tumor necrosis and vascular damage in experimental Burkitt lymphomas." (PMID 34960234, 2021).
cardiac hypertrophy (2 papers, 2022 to 2025). "This was associated with cardiac hypertrophy and dysfunction dependent upon CXCL10 signalling." (PMID 35090403, 2022).
cerebral toxoplasmosis (2 papers, 2018 to 2022). Infections of the brain caused by the protozoan toxoplasma gondii that primarily arise in individuals with immunologic deficiency syndromes (see also aids-related opportunistic infections). "In murine ocular and cerebral toxoplasmosis, there is a significant increase in the expression levels of CXCL10 and CXCL11 over the course of infection." (PMID 29459857, 2018).
cervical intraepithelial neoplasia (2 papers, 2021 to 2022). "In the present study, CXCL10 was substantially upregulated both in cervical tissues of HPV infected patients with cervical intraepithelial neoplasia (CIN) or CSCC, as well as in HPV16 E6/E7 transgenic murine cervix." (PMID 34422627, 2021). "Serum levels of CXCL10 and SCC-Ag were measured by ELISA or automated immunoassay in 345 participants, including 189 patients with different stages of CESC, 75 patients with cervical intraepithelial neoplasia, and 81 healthy individuals." (PMID 36207693, 2022).
Chlamydia infection (2 papers, 2021). "Chlamydia infection also induced a significant mRNA upregulation of the chemokines CXCL10, CXCL11, CCL20, and RANTES." (PMID 34684219, 2021). "Next, we explored whether the expression of IFN-γ and IFN-γ induced genes was altered in FP- and BUD-treated lung tissues, including the typical, inducible defence genes against Chlamydia infection, such as indoleamine 2,3-dioxygenase 1 (IDO1), IDO2, MIG/CXCL9, IP-10/CXCL10 and I-TAC/CXCL11." (PMID 33799333, 2021).
Chlamydial infection (2 papers, 2014 to 2017). "Following chlamydial infection, we further observed a secretion of pro-inflammatory IP-10 (CXCL 10)." (PMID 25019934, 2014).
chronic fatigue syndrome (2 papers, 2020 to 2021). "CXCL10 (IP-10) is a small-molecular-weight pro-inflammatory chemokine produced by many cells, including microglia and the CXCL10 protein was found upregulated in GWI serum and serum from myalgic encephalomyelitis patients." (PMID 34253711, 2021).
clear cell carcinoma (2 papers, 2023 to 2025). "By reprogramming TAMs toward an M1 phenotype, these interventions may help overcome immune exclusion, particularly in subtypes like clear cell carcinoma (CCC), where CXCL10-producing macrophages are scarce." (PMID 40330466, 2025).
Clear Cell Renal Cell Carcinoma (2 papers, 2019 to 2022). "It had been reported that the calculated score based on the expression of CXCL11, CXCL9, and CXCL10 could stratify nonmetastatic clear-cell renal cell carcinoma (ccRCC) patients into different risk subgroups." (PMID 31781593, 2019).
conjunctivitis (2 papers, 2018 to 2023). Inflammation of the conjunctiva of the eye. "Likewise, conjunctivitis found in our cohort was linked to significant increases in CXCL10 (p = 0.0332), followed by IL-4 (p = 0.0112) and IFN-γ (p = 0.0306) levels." (PMID 37235332, 2023). "Meanwhile, conjunctivitis was linked to elevated levels of IFN-γ (p = 0.0306), IL-4 (p = 0.0112), and CXCL10 (p = 0.0332)." (PMID 37235332, 2023).
discoid lupus erythematosus (2 papers, 2021 to 2025). A chronic, autoimmune skin condition that manifests with a red, scaling rash, most often found on the face, ears, and scalp; these lesions often lead to permanent scarring and dyspigmentation. "Importantly, these GREM1+ fibroblasts were consistently present across CLE subtypes, including both subacute cutaneous lupus (SCLE) and discoid lupus erythematosus (DLE), with the same localization, associated chemokines (CXCL10, CCL5), and associated cell types (pDC, T cells)." (PMID 40409678, 2025).
eczema (2 papers, 2017 to 2023). "In skin lesions from eczema, the mean percentages of inflammatory cells expressing CXCL9, CXCL10, CXCL11 and CXCR3 were 4.8% ± 5.8%, 5.2% ± 6.3%, 63.2% ± 15.7% and 25.2% ± 13.0%, respectively." (PMID 28436448, 2017).
endometritis (2 papers, 2021 to 2022). An acute or chronic, usually bacterial infectious process affecting the endometrium. "A total of 12 pregnancy regulated genes were upregulated only in healthy cows and not cows after uterine infection, including CXCL10, ISG15 and TRANK1." (PMID 35358206, 2022). "Similarly, expressions of IFNT, ISG15, CXCL10, PPARG, RXRG, SLC2A1, and SLC27A6 proteins were greater and MUC1 was lower in the endometrium of cows without endometritis compared with cows with endometritis (p < 0.05)." (PMID 33920430, 2021).
enteritis (2 papers, 2017 to 2024). Inflammation of the small intestine. "Following DSS-induced enteritis, there was a significant increase in the protein levels of CXCL10 and TNF-α, coupled with a notable decrease in IL10 and CCL17." (PMID 38774206, 2024). "Both Que and RU.521 could significantly reduce the protein levels of CXCL10 and TNF-α while increasing the protein levels of IL10 and CCL17 following the induction of enteritis." (PMID 38774206, 2024).
esophageal adenocarcinoma (2 papers, 2020 to 2024). A malignant tumor with glandular differentiation arising predominantly from Barrett mucosa in the lower third of the esophagus. "Importantly, CXCL10 appears to be an important prognostic marker for response to ICIs,40, 41, 42 including in advanced oesophageal adenocarcinoma." (PMID 38744099, 2024).
gastroenteritis (2 papers, 2021 to 2022). An inflammatory disorder that affects the upper and lower gastrointestinal tract. "Several patients suffered from other treatment-related infections, particularly gastroenteritis, and therefore it is difficult to assign elevated CXCL10 levels unambiguously to a single infection." (PMID 36142860, 2022). "In a clinical study of hospitalized HuNoV gastroenteritis patients, an elevated serum level of CXCL10 was observed." (PMID 33494515, 2021).
geographic atrophy (2 papers, 2016 to 2022). "Up-regulation of Ccl2, Cxcl1, Cxcl10, and Cxcl11 are present in all forms of AMD, and the Ccl2/Ccr2 axis is implicated in the pathogenic accumulation of macrophages to the outer retina in models that feature aspects of either CNV or geographic atrophy, such as light damage." (PMID 26911327, 2016).
glomerulonephritis (2 papers, 2025). A renal disorder characterized by damage in the glomeruli. "In fact, the cytokine was assumed to attenuate CXCL10/CXCR3‐dependent infiltration of T lymphocytes during glomerulonephritis." (PMID 41287825, 2025). "Indeed, in the kidney, epithelial cells are the primary source of CXCL10 and prednisolone reduces its expression, thereby lowering CD4pos T-cell kidney infiltration in the context of glomerulonephritis." (PMID 41229420, 2025).
haemorrhage (2 papers, 2023 to 2025). "The downregulation of chemokines, CXCL10 and CXCL11, would reduce the recruitment of immune cells, including M1 macrophages, to areas with thrombotic or hemorrhagic plaques." (PMID 40969943, 2025).
hemorrhagic stroke (2 papers, 2018 to 2025). A stroke caused by a bleed on the brain. "Induced expression of both CXCL10 and CCL2 has also been observed in human cases of ischemic and hemorrhagic stroke." (PMID 40867143, 2025).
hepatitis D (2 papers, 2014 to 2025). "We previously demonstrated that high levels of CXCL10 can be detected in the serum of hepatitis delta patients and that levels of CXCL10 further increased during PEG-IFNα therapy." (PMID 25072849, 2014).
herpesvirus infection (2 papers, 2013 to 2022). "The CXCL10 and 9 chemokines and their receptors on NK and T cells are critical weapons of the infected host to control herpesvirus infections." (PMID 24068939, 2013). "The chemokine genes CXCL10 and CXCL9 and their receptors on NK and T cells are critical weapons of the infected host to control herpesvirus infections." (PMID 24068939, 2013). "Moreover, the delivery of exogenous CXCL10 boosts the number and function of HSV-1 specific CD8+ T cells and improves the protection against recurrent herpesvirus infection and disease in mice." (PMID 35337341, 2022).
hyperthyroidism (2 papers, 2020 to 2021). Overactivity of the thyroid gland resulting in overproduction of thyroid hormone and increased metabolic rate. "A prevalent Th1-immune response (not related to the hyperthyroidism per se, but to the autoimmune process) is reported in the immune-pathogenesis of GD and GO; Th1-chemokines (CXCL9, CXCL10, CXCL11) and the (C-X-C)R3 receptor are crucial in this process." (PMID 33935970, 2021).
ileitis (2 papers, 2009 to 2014). "Another example of a secreted protein associated with probiotic activity is the prt-P-encoded protease of L. paracasei that degrades secreted CXCL10 (also called IP-10), resulting in reduced lymphocyte recruitment in an ileitis model." (PMID 24459463, 2014).
interstitial nephritis (2 papers, 2017 to 2025). Inflammation of the renal tubules and supporting tissues of the kidney. "We have previously shown that urinary presepsin increases in interstitial nephritis; however, whether it is elevated in the conditions mentioned as confounding factors for CXCL9 and CXCL10 remains unclear and warrants further investigation." (PMID 41306150, 2025).